CDK9 (cyclin dependent kinase 9)
Diseases named in the same sentence as CDK9 in open-access papers (continued):
Sharing a sentence is not in itself a finding about the gene and the disease.
invasive breast carcinoma (1 paper, 2021). A carcinoma that infiltrates the breast parenchyma. "CDK9 was found to be highly expressed in invasive breast carcinoma (fold change = 1.725) in the TCGA dataset, and in invasive lobular breast carcinoma (fold change=1.778) in Turashvili’s dataset." (PMID 33686962, 2021).
left ventricular hypertrophy (1 paper, 2012). Enlargement of the LEFT VENTRICLE of the heart. "It has been reported that Cdk9 activity was demonstrated to be necessary for hypertrophy in cardiomyocytes in vitro and that heart-specific activation of Cdk9 was found to provoke left ventricular hypertrophy (LVH) in mice, suggesting that the increase in P-TEFb function is associated with LVH." (PMID 23300697, 2012).
liver fibrosis (1 paper, 2022). "SNS-032 decreases active HSCs to alleviate hepatic fibrosis by inducing the apoptosis of active HSCs and inhibiting their activation and proliferation by inhibiting the expression of CDK9 and blocking the phosphorylation of RNAP II and its downstream factors." (PMID 36313366, 2022). "These pieces of evidence strongly suggest that CDK9 is a potential powerful target against liver fibrosis." (PMID 36313366, 2022). "The CDK9 inhibitor SNS-032 has definite effects in liver fibrosis treatment in vivo and in vitro." (PMID 36313366, 2022). "Although SNS-032 is a CDK9 inhibitor and shows good effects in liver fibrosis treatment, the mechanisms of CDK9 in the development of liver fibrosis remain unclear." (PMID 36313366, 2022). "However, the role of CDK9 inhibitors in the development of liver fibrosis is unclear." (PMID 36313366, 2022).
lung disease (1 paper, 2019). "Additionally, transcription elongation is involved in IFN-stimulated gene (ISG) expression induced by RSV, and cyclin-dependent kinase 9 (CDK9) activity may serve as a potential target for immunomodulation in RSV-associated lung disease." (PMID 31223533, 2019).
lung fibrosis (1 paper, 2024). "Importantly, the involvement of CDK9 in the senescence pathway presents a promising therapeutic target for treating lung fibrosis." (PMID 39040475, 2024). "In line with the upregulation of CDK9 proteins by Western blots, the expression of CDK9 was significantly higher evaluated by immunostaining in the BLM model of lung fibrosis in mice." (PMID 39040475, 2024).
lymph node metastasis (1 paper, 2021). "In this study, CDK9 was found to be highly expressed in EC tissues, and its high expression was correlated with histological grade, FIGO stage, depth of muscular invasion, and lymph node metastasis." (PMID 35071768, 2021).
monocytic acute leukemia (1 paper, 2016). "Moreover, Flavopiridol (CDK9 inhibitor) could inhibit THP-1 cell (monocytic acute leukemia cell line) proliferation by targeting CDK9." (PMID 26636538, 2016).
myocardial infarction (1 paper, 2022). Gross necrosis of the myocardium, as a result of interruption of the blood supply to the area, as in coronary thrombosis. "In vivo, inhibition of CDK9 shortened the time window of cardiac regeneration after apical resection (AR) in neonatal mice, while overexpression of CDK9 significantly promoted mature cardiomyocytes (CMs) to re-enter the cell cycle and cardiac repair after myocardial infarction (MI) in adult mice." (PMID 36082129, 2022).
neuropathic pain (1 paper, 2019). Chronic pain caused by damage to nerve fibers. "SNL downregulated spinal Hes1 expression and its suppression of the CDK9 and RNAPII recruitment and RNAPII phosphorylation on the mGluR5 promoter segments to mediate the development of neuropathic pain." (PMID 31454988, 2019).
oral cancer (1 paper, 2025). "Screening of the data revealed eight TRGs (TGFB3, LTBP2, BMP2, TGFB1, ACVR1, CDK9, SLC20A1, and SMURF2) with non-zero coefficients, indicating their association with the prognosis of oral cancer patients." (PMID 38698292, 2025).
osteoporosis (1 paper, 2018). A condition of reduced bone mass, with decreased cortical thickness and a decrease in the number and size of the trabeculae of cancellous bone (but normal chemical composition), resulting in increased fracture incidence. "Summary, CDK9 is a potential therapeutic target to prevent osteolysis and osteoporosis by flavopiridol treatment." (PMID 29773986, 2018).
prostate adenocarcinoma (1 paper, 2022). "Similarly, CDK9 expression is associated with unfavorable prognosis in KIRC and prostate adenocarcinoma (PRAD)." (PMID 36577800, 2022).
stomach cancer (1 paper, 2022). "With this approach we identified MDM2 ligase, coupled with inhibitors of the targets BCL2L1, BRD4, CDK9, PLK1 and MCL1 in stomach tumor tissue, as a therapeutic strategy." (PMID 35249548, 2022).
T-cell lymphomas (1 paper, 2025). "In conjunction with prior screening efforts, this data suggests that CDK9 is a viable therapeutic vulnerability in genetically high-risk T-cell lymphomas." (PMID 41309546, 2025). "These transcriptional programs, prevalent in T-cell lymphomas, were directly associated with both CDK9 expression and cell proliferation." (PMID 41309546, 2025). "In order to determine the extent to which MCL-1 loss is a significant mechanism of action for CDK9 antagonism in the T-cell lymphomas, BH3 profiling was performed and cell lines stratified by MCL-1 dependence." (PMID 41309546, 2025). "In summary, we have shown that CDK9 is a dependency and therapeutic vulnerability across diverse T-cell lymphoma subsets, including those that are MCL-1 dependent." (PMID 41309546, 2025). "As anticipated, MCL-1 dependent T-cell lymphomas were highly sensitive to CDK9 antagonism with AZD4573, culminating in PARP and caspase 3 cleavage within 6 h of treatment." (PMID 41309546, 2025). "The extent to which MCL-1 dependence confers sensitivity to CDK9 antagonism was examined next, as a subset of T-cell lymphomas are MCL-1 dependent." (PMID 41309546, 2025). "We observed that transcriptional cyclin dependent kinase 9 (CDK9) activation regulates diverse oncogenic transcriptional programs in these aggressive T-cell lymphomas and is thus a novel therapeutic vulnerability." (PMID 41309546, 2025). "Strong CDK9 expression was detected by immunohistochemistry in 90% of human T-cell lymphomas examined." (PMID 41309546, 2025). "Therefore, CDK9 is a therapeutic vulnerability across genetically and transcriptionally diverse T-cell lymphomas, including those for which GATA-3 is oncogenic." (PMID 41309546, 2025). "Collectively then, we have identified novel and complementary GATA-3 dependent and independent mechanisms by which CDK9 regulates the growth and survival of GATA-3 driven T-cell lymphomas." (PMID 41309546, 2025). "Components of the SWI/SNF complex are recurrently altered in many T-cell lymphomas, and SMARCA4 (BRG1) is dephosphorylated upon CDK9 inhibition, contributing to reactivation of gene expression." (PMID 41309546, 2025). "Therefore, we sought to examine the extent to which CDK9 antagonism is a therapeutic vulnerability in vivo using a GATA-3 dependent, but MCL-1 independent, T-cell lymphoma model." (PMID 41309546, 2025). "However, we also observed that MCL-1 independent T-cell lymphoma cells were also sensitive to both AZD4573 and an independent CDK9 antagonist [enitociclib,]." (PMID 41309546, 2025). "CDK9 dependent transcriptional programs that are not dependent on GATA-3 may be significantly enriched in GATA-3 dependent T-cell lymphomas." (PMID 41309546, 2025). "Consequently, the epigenetic effects of CDK9 inhibition, while incompletely understood, were not examined, but are relevant in a T-cell lymphoma context." (PMID 41309546, 2025). "Consequently, CDK9 antagonism, by impairing rRNA processing, rapidly culminates in nucleolar stress, and the subsequent termination of RiBi, providing a novel MCL-1 independent mechanism by which CDK9 antagonism is a therapeutic vulnerability in GATA-3 dependent T-cell lymphomas." (PMID 41309546, 2025).
Urothelial bladder cancer (1 paper, 2022). "CDK9 expression was prognostic in the TCGA cohort, and its high expression predicts longer overall survival in urothelial bladder cancer." (PMID 35326643, 2022). "Urothelial bladder cancer patients with higher CDK9 expression had a higher 5-year overall survival rate when compared to the low CDK9 expression group." (PMID 35326643, 2022).
verruca vulgaris (1 paper, 2019). "The main objective of this study is to examine the antiviral effect of the CDK9 inhibitor FIT039 in the treatment of verruca vulgaris, or warts, caused by HPV." (PMID 31399147, 2019). "We present the design of a double-arm phase I/II study to evaluate the safety and efficacy of the CDK9 inhibitor FIT039 in the treatment of verruca vulgaris, or common warts." (PMID 31399147, 2019).
cancer (227 papers, 2009 to 2026). A tumor composed of atypical neoplastic, often pleomorphic cells that invade other tissues. "The overexpression of genes that control tumor cell proliferation, survival, cell cycle regulation, DNA damage repair, and metastasis has been associated with the excessive activity of CDK9 in cancer." (PMID 39404419, 2024). "AZD-4573 is a potent CDK9 inhibitor that specifically reduces the expression of cancer-causing genes such as MCL-1." (PMID 39404419, 2024). "To comprehensively investigate the therapeutic potential of targeting CDK9 in solid tumors, we analyzed the drug screening data from the Cancer Therapeutics Response Portal (CTRP) to identify associations between CDK9 expression and drug sensitivity." (PMID 39254172, 2024). "In AR-independent contexts, we posit that effects on other CDK9 downstream targets are the dominant mechanism underlying CDKI-73’s anti-cancer activity." (PMID 39117800, 2024). "We now have confirmed overexpression of CDK9 in cancer tissues, with low expression associated with poorer survival in a subset of CRC patients." (PMID 36979907, 2023). "The overexpression of CDK9 is frequently reported in cancers and is often associated with unfavorable prognoses." (PMID 36374405, 2023). "It was repeatedly shown that Cdk9 promotes proliferation, survival and metastasis of cancer cells and high Cdk9 expression is associated with unfavorable outcome of different types of cancers." (PMID 35563824, 2022). "Overexpression of cyclin-dependent kinase 9 has been recently linked to increased cancer proliferation, faster progression, and worse prognosis." (PMID 35326643, 2022). "For example, whereas loss of CDK9 produces responses in cancer cells that resemble the loss of key components of the transcriptional machinery (e.g., RNAPII subunits), this is not the case for CDK7." (PMID 36577800, 2022). "Cancer cell-selective induction of the excessive DNA damage in response to CDK9 inhibitor treatment is likely to cause mutations in the malignant cells." (PMID 35164752, 2022). "As the regulatory functions of CDK9 in gene expression continue to expand, a number of human pathologies, including cancers, have been associated with aberrant CDK9 activity, underscoring the need to properly regulate CDK9." (PMID 34146121, 2021). "Instead, cancers are often associated with increased CDK9 function resulting from modulation of CDK9 association with regulatory proteins and/or increased targeting to genes." (PMID 34146121, 2021). "Significantly enhanced activity of CDK9 is observed in multiple cancer types, which is universally associated with significantly shortened Overall Survival (OS) of the patients." (PMID 34062779, 2021). "Among them, since the transcription-associated CDK9 represents the sentry of cell transcriptional homeostasis, it can be a valuable target for managing cancers in which the transcriptional machinery is dysregulated by tumor-driver oncogenes." (PMID 32903585, 2020). "In keeping with its central role in transcription regulation, CDK9 has also been implicated in abnormal cellular responses linked to cancer and HIV." (PMID 27715402, 2016). "Additionally, CDK5 and CDK9 play roles in transcriptional regulation and apoptosis; thus, their inhibition by Dinaciclib can enhance cancer cell susceptibility to programmed cell death." (PMID 40076816, 2025). "CDK9 is associated with various cancers linked to dysregulated transcriptional machinery." (PMID 40361480, 2025). "However, it is noteworthy that CDK9 mutations or amplifications rarely occur in cancer patients, especially in NSCLC 11, raising the concerns about the specificity of CDK9 inhibitors and their potential impact on normal cells." (PMID 40860160, 2025).
cancer (continued). "Indeed, implementation of CDK9 inhibition as a therapeutic strategy for cancer has been hampered by the poor selectivity and associated off target toxicity of CDK9 inhibitor drugs that have been clinically tested, predominantly in the context of blood cancer." (PMID 38001268, 2024). "Deregulated kinase activity of CDK9 of the PTEFb hetero-dimer is associated with cancer." (PMID 37298753, 2023). "We also found that SETD2-deficient cancer cells were more sensitive to transcriptional inhibitors, including the CDK9 inhibitor dinaciclib, which is in accordance with the notion that SETD2 loss–induced upregulation of oncogenic transcriptional programs is required for tumor maintenance." (PMID 36810256, 2023). "Since CDK7, CDK8/19, CDK12/13, or CDK9 are associated with basal RNA transcription, it seemed a reasonable strategy to selectively target these CDKs, as cancer cells may be particularly susceptible to selective suppression." (PMID 35053461, 2022). "This hypothesis is supported by the fact that CDK9 inhibition causes DNA damage and sensitizes cancer cells to genotoxic agents." (PMID 35708495, 2022). "However, in cancers where somatic mutations are more frequent, the genomic instability, including early deletions of 9q, may decrease the expression of CDK9." (PMID 35326643, 2022). "Our data indicate that systemic interference with Cdc7/Cdk9 activity results in a strong suppression of the adaptive immune response and likely affects not only the adaptive response to tumors but also the ability of the immune system to react to cancer-associated opportunistic infections." (PMID 31402912, 2019). "In the context of human disease, hyperactivation of CDK9 leads to the development of various cancers, including acute myeloid leukemia." (PMID 40954203, 2026). "Our lead compound, 13 (dCDK9-010), recruits the MDM2 E3 ligase to induce proteasome-dependent degradation of CDK9 and all cyclin T isoforms across diverse cancer models." (PMID 41970231, 2026). "In addition, we show that these CDK9 inhibitors reduced gene expression associated with differentiation state and stemness, which might affect cancer stem cell population, cell differentiation and/or cancer cell plasticity (e.g. proliferation/dormancy and epithelial-to-mesenchymal plasticity)." (PMID 41505030, 2026). "Collectively, this underscores the potential of targeting master transcriptional regulators, such as P-TEFb/CDK9, as a robust strategy for various cancer types." (PMID 41505030, 2026). "Dysregulation of the PP2A–integrator–cyclin-dependent kinase 9 (CDK9) axis is commonly observed in various cancers and can arise from genetic alterations or overexpression of inhibitory molecules." (PMID 41020855, 2025). "This gene promotes the proliferation, migration, and invasion of cancer-derived cell lines by regulating CDK9, a key cell cycle regulator." (PMID 40508156, 2025). "Treatment with the CDK2/9 inhibitor CYC065 (Fadraciclib) having antagonism of CDK2 > CDK9 substantially increased the presence of cancer cells with multipolar mitotic spindles across diverse aneuploid cancer cells." (PMID 40232858, 2025). "CDK9 promotes the survival of cancer cells by upregulating the expression of transient anti-apoptotic proteins, including Mcl-1." (PMID 40361480, 2025). "Dysregulated CDK9 activity is observed in various cancers, where it promotes cancer progression by regulating RNA transcription, DNA repair, recruitment of transcription factors, and tumor immune evasion." (PMID 40975978, 2025). "CDK9 (cyclin-dependent kinase 9), a catalytic subunit of the transcription elongation factor P-TEFb, is considered a promising target for cancer therapy." (PMID 40655944, 2025). "Among them, St.38 exhibited strong antiproliferative activity across multiple cancer cell lines and potently inhibited CDK9, HDAC1, and HDAC3." (PMID 41440016, 2025).